ANK2 (ankyrin 2)
Description:
Plays an essential role in the localization and membrane stabilization of ion transporters and ion channels in several cell types, including cardiomyocytes, as well as in striated muscle cells. In skeletal muscle, required for proper localization of DMD and DCTN4 and for the formation and/or stability of a special subset of microtubules associated with costameres and neuromuscular junctions. In cardiomyocytes, required for coordinate assembly of Na/Ca exchanger, SLC8A1/NCX1, Na/K ATPases ATP1A1 and ATP1A2 and inositol 1,4,5-trisphosphate (InsP3) receptors at sarcoplasmic reticulum/sarcolemma sites. Required for expression and targeting of SPTBN1 in neonatal cardiomyocytes and for the regulation of neonatal cardiomyocyte contraction rate. In the inner segment of rod photoreceptors, required for the coordinated expression of the Na/K ATPase, Na/Ca exchanger and beta-2-spectrin (SPTBN1) (By similarity). Plays a role in endocytosis and intracellular protein transport. Associates with phosphatidylinositol 3-phosphate (PI3P)-positive organelles and binds dynactin to promote long-range motility of cells. Recruits RABGAP1L to (PI3P)-positive early endosomes, where RABGAP1L inactivates RAB22A, and promotes polarized trafficking to the leading edge of the migrating cells. Part of the ANK2/RABGAP1L complex which is required for the polarized recycling of fibronectin receptor ITGA5 ITGB1 to the plasma membrane that enables continuous directional cell migration (By similarity).
Synonyms: ANK-2; FAP87; CFAP87; LQT4; brank-2
Tractability: Antibody: UniProt places it where antibodies can reach, with high confidence; its Gene Ontology location is reachable by antibodies, with medium confidence; the Human Protein Atlas places it where antibodies can reach. PROTAC: ubiquitination databases record sites on it; its protein half-life has been measured.
Gene: Protein-coding gene on chromosome 4 (112,818,032 to 113,384,231, forward strand). Ensembl gene ENSG00000145362.
Subcellular location: Cytoplasm, cytoskeleton; Membrane; Cytoplasm, myofibril, sarcomere, M line; Apical cell membrane; Cell membrane; Postsynaptic cell membrane; Early endosome; Recycling endosome; Lysosome; Mitochondrion; Cytoplasm, myofibril, sarcomere, Z line; Cell membrane, sarcolemma, T-tubule
Subcellular location (Human Protein Atlas): Acrosome; Plasma membrane
Pathways (Reactome):
Developmental Biology: Interaction between L1 and Ankyrins
Vesicle-mediated transport: COPI-mediated anterograde transport
Gene Ontology:
Molecular function: enzyme binding; phosphorylation-dependent protein binding; protein binding; protein kinase binding; spectrin binding; transmembrane transporter binding; ATPase binding; channel activator activity; cytoskeletal anchor activity; potassium channel activator activity; protein-macromolecule adaptor activity; structural constituent of cytoskeleton
Biological process: atrial cardiac muscle cell action potential; atrial septum development; intracellular protein localization; positive regulation of gene expression; positive regulation of potassium ion import across plasma membrane; protein localization to endoplasmic reticulum; protein localization to plasma membrane; regulation of atrial cardiac muscle cell action potential; regulation of calcium ion transport; regulation of cardiac muscle cell contraction; regulation of cardiac muscle contraction; regulation of cardiac muscle contraction by calcium ion signaling; regulation of cardiac muscle contraction by regulation of the release of sequestered calcium ion; regulation of heart rate; regulation of heart rate by cardiac conduction; regulation of release of sequestered calcium ion into cytosol; regulation of SA node cell action potential; regulation of ventricular cardiac muscle cell membrane repolarization; SA node cell to atrial cardiac muscle cell communication; ventricular cardiac muscle cell action potential; atrial cardiac muscle cell to AV node cell communication; intracellular calcium ion homeostasis; membrane depolarization during SA node cell action potential; positive regulation of calcium ion transport; protein localization to cell surface; and 12 more
Cellular component: basolateral plasma membrane; membrane; plasma membrane; A band; apical plasma membrane; costamere; cytosol; early endosome; intercalated disc; lysosome; M band; mitochondrion; neuron projection; photoreceptor inner segment membrane; postsynaptic membrane; recycling endosome; sarcolemma; T-tubule; Z disc; cytoskeleton
Genetic constraint (gnomAD): Loss-of-function variants: 81 observed, 359.56 expected, observed/expected ratio (o/e) 0.23, 90% interval 0.19 to 0.27. The upper end of that interval is the gene's LOEUF score, 0.27, which puts it in group 1 of 6, group 1 being the genes least tolerant of losing a copy. Missense variants: 4,179 observed, 5,007.4 expected, observed/expected ratio (o/e) 0.83, 90% interval 0.81 to 0.86. Synonymous variants: 1,737 observed, 1,847 expected, observed/expected ratio (o/e) 0.94, 90% interval 0.9 to 0.98.
Gene-disease validity (ClinGen):
ClinGen rates the evidence that ANK2 causes each of these diseases.
complex neurodevelopmental disorder (autosomal dominant): Definitive. A disorder that involves more than one phenotype associated with the central nervous system, including but not limited to intellectual disability, autism, and seizures (epilepsy).
Brugada syndrome (autosomal dominant): Disputed. A genetically heterogeneous condition characterized by complete or incomplete right bundle branch block accompanied by ST elevation in leads V1-V3.
catecholaminergic polymorphic ventricular tachycardia (autosomal dominant): Disputed. Catecholaminergic polymorphic ventricular tachycardia (CPVT) is a severe genetic arrhythmogenic disorder characterized by adrenergically induced ventricular tachycardia (VT) manifesting as syncope and sudden death.
long QT syndrome (autosomal dominant): Disputed.
Homologues: Orthologues: chimpanzee ANK2 (99% identical), macaque ANK2 (96% identical), pig ANK2 (88% identical), dog ANK2 (87% identical), rabbit ANK2 (84% identical), mouse Ank2 (84% identical), guinea pig ANK2 (83% identical), rat Ank2 (83% identical), tropical clawed frog ank2 (62% identical), zebrafish ank2a (45% identical). Paralogues in human: ANK3 (41% identical), ANK1 (24% identical), ASB7 (3% identical).
Diseases named in the same sentence as ANK2 in open-access papers:
ANK2 is named in the same sentence as 101 diseases in open-access papers, as found by Europe PMC text mining. Sharing a sentence is not in itself a finding about the gene and the disease. The quoted sentences say what the papers report.
cardiac arrhythmia (22 papers, 2007 to 2026). Any disturbances of the normal rhythmic beating of the heart or MYOCARDIAL CONTRACTION. "The risk of sudden cardiac death in offspring depends on the presence of these genetic variants, with ANK2 carriers at increased risk for arrhythmias." (PMID 41287789, 2025). "ANK2 variants have been linked to an inherited condition known as “ankyrin-B syndrome”, which manifests as a spectrum of cardiac arrhythmias and cardiomyopathy." (PMID 39867173, 2025). "Our current review examines the relationship between ANK2 variants and specific heart conditions, summarizing recent findings on the genetic and molecular mechanisms underlying ANK2-related arrhythmias and structural abnormalities." (PMID 39867173, 2025). "Current clinical efforts should therefore focus on monitoring carriers of ANK2 functional variants for arrhythmia and cardiomyopathy, along with symptomatic and treatment and control of co-morbidities." (PMID 35990955, 2022). "Over time, several other arrhythmias and conduction anomalies have been associated with ANK2 variants including catecholaminergic polymorphic ventricular tachycardia (CPVT), bradycardia, and WPW." (PMID 35990955, 2022). "Certain ANK2 loss-of-function variants are associated with a broad spectrum of cardiac phenotypes including arrhythmia, conduction abnormalities, and cardiomyopathy." (PMID 35990955, 2022). "Variants in the ankyrin-B or ankyrin-2 genes will result in several cardiac arrhythmias ranging from sinus node dysfunction to life-threatening arrhythmias." (PMID 35224819, 2022). "At the same time, a human mutation in ANK2 has been shown to alter interaction with βII-spectrin resulting in severe cardiac arrhythmia, supporting a role for spectrin proteins in human cardiac pathophysiology." (PMID 33946725, 2021). "Although AnkB is commonly associated with arrhythmias, variants in ANK2 have also been associated with structural heart disease." (PMID 32023981, 2020). "The ANK2 p.Q1283H variant within ZU5c was recently associated with arrhythmia, potentially due to loss of PP2A activity and altered phosphorylation of RyR2." (PMID 32023981, 2020). "As described later, human ANK2 variants that alter spectrin-binding are now linked with potentially fatal forms of cardiac arrhythmia." (PMID 29163198, 2017). "Our studies and genome-wide association studies have shown that arrhythmias arise not only due to mutations in ion channels but also due to mutations in genes encoding cytoskeletal proteins (β2 spectrin), adapter proteins (Ankyrin 2), ECM, fibrosis, cardio-genesis, and cell-cell coupling." (PMID 39328831, 2024). "Given that seizures can be linked to cardiac arrhythmias and the fact that some cardiac-associated ANK2 variants are linked with seizures it would be worth investigation to determine if the seizures are a result of the arrhythmia or independent and owed to dysfunction in the brain." (PMID 35990955, 2022). "Furthermore, ANK2 loss-of-function variants were extensively related with inherited cardiac arrhythmias, even with BrS, although this relationship is currently under debate." (PMID 34884836, 2021). "Loss-of-function variants in ANK2 (encodes ankyrin-B) cause a dominantly-inherited cardiac arrhythmia with increased risk for sudden cardiac death, initially termed type 4 long QT syndrome, and more recently renamed sick sinus syndrome with bradycardia or the “ankyrin-B syndrome” (; OMIM)." (PMID 17940615, 2007). "This raises the possibility that ANK2 variants may play akey role in a complex disease etiology that could be oligogenic or polygenic.Given the complexity involved, further research is essential to understand howANK2 variants contribute to the pathophysiology of arrhythmias." (PMID 39867173, 2025). "Previous studies have demonstrated that mutations in ANK2 and PKP2 have been associated with ion channel dysfunction leading to cardiac arrhythmias." (PMID 34281161, 2021).
cardiac arrhythmia (continued). "The co‐existence of QT prolongation on electrocardiogram, autism, and a positive family history of cardiac arrhythmia or sudden death may provide important clues in the clinical diagnosis of ANK2‐related epilepsy." (PMID 39962910, 2025). "To date, animal models for human arrhythmias have generally been knock-out or transgenic overexpression models and thus the direct impact of ANK2 variants on cardiac structure and function in vivo is not clearly defined." (PMID 37182735, 2023). "A role of ankyrin-B (ANK2) in cardiac arrhythmias was first evidenced by the identification of a common mutation (E1425G) in patients from a French kindred presenting with atypical LQTS, initially referred to as LQT4 and then renamed ankyrin-B syndrome." (PMID 34572065, 2021). "Moreover, the abnormal function of ankyrin-2 (ANK2) may lead to sinoatrial node disease and ankyrin-B-related cardiac arrhythmia in humans." (PMID 35924220, 2022). "Importantly, a subset of ANK2 variants associated with cardiac arrhythmias failed to rescue the metabolic defects in Ank2−/− adipocytes, calling to attention additional cardiovascular risk considerations for individuals with known ANK2 cardiac arrhythmia variants." (PMID 35990955, 2022). "Moreover, another calcium ion transport-related gene ANK2 may lead to cardiac arrhythmia." (PMID 35924220, 2022). "Understanding the genetic basis of these conditions is essential for developingeffective treatments and interventions for managing cardiac arrhythmias and SCD.Several studies have investigated the role and mechanisms of ANK2 genevariants in cardiovascular diseases." (PMID 39867173, 2025).
autism (16 papers, 2017 to 2026). Persistent deficits in social interaction and communication and interaction as well as a markedly restricted repertoire of activity and interest as well as repetitive patterns of behavior. "Variants in ANK2 genes are initially reported in long QT syndrome and autism." (PMID 39962910, 2025). "We identified 178 phosphorylation sites with higher phosphorylation level on the left striatum and 124 on the right among 142 autism-related proteins, including ANK2, CaMK2B and SHANK3." (PMID 40890295, 2025). "In contrast, for 134 autism-associated genes, including ASH1L, ANK2 and SHANK3, we could identify at least one carrier of an S-LoF among the undiagnosed individuals, suggesting lower effect sizes on autism diagnosis." (PMID 37365347, 2023). "RFX transcription factors bind to a X-box consensus motif, which was found by the authors in some neuronal specific enhancers and/or promoters of autism risk genes (such as AP2S1, KDM6B, ANK2, NONO, and MYT1L)." (PMID 34768579, 2021). "Around 50% and around 30% of the association signal, for MAP1A and for ANO8, respectively, was driven by rare deleterious variants in individuals diagnosed with ADHD only (without comorbid schizophrenia, ID or autism), whereas the ANK2 signal was driven mainly by ADHD with co-occurring autism or ID." (PMID 41224997, 2026).
cardiomyopathy (11 papers, 2017 to 2025). A disease of the heart muscle or myocardium proper. "Beyond inherited arrhythmias, loss-of-function variants in ANK2 have also been associated with cardiomyopathy, such as hypertrophic cardiomyopathy, dilated cardiomyopathy, and LV dysfunction." (PMID 35990955, 2022). "Three cases (34, 286 and 290) had one variant in a cardiomyopathy gene and one in a channelopathy gene (CSRP3 and TRPM4, PKP2 and ANK2, MYH7 and KCNH2, respectively)." (PMID 30615648, 2019). "ANK2 variants are associated with cardiovascular phenotypes including sinus node disease, atrial fibrillation, heart rate variability, catecholaminergic polymorphic ventricular tachycardia (CPVT), ACM, cardiomyopathy, syncope, and sudden cardiac death." (PMID 32023981, 2020). "These relatives had supraventricular heart rhythm abnormalities without cardiomyopathy associated with rare JUP and ANK2 variants of uncertain significance." (PMID 41287789, 2025).
long QT syndrome (11 papers, 2010 to 2025). "We further identified ANK2 variants (causative of long-QT syndrome, OMIM *106410), one classified as likely pathogenic and one as VUS in 1 patient each." (PMID 30091983, 2018). "Loss of function of Ankyrin B (ANK2) is associated with long QT syndrome and sudden cardiac death in humans and mice." (PMID 22934047, 2012). "ANK2 variants can cause long QT syndrome four and arrhythmia syndrome." (PMID 35309141, 2022). "PVs and LPVs in the ABCC9, AKAP9, ANK2, and SCN10A have been implicated in conduction defects and arrhythmias, particularly the long QT syndromes and conduction defects." (PMID 34790974, 2021). "ANK2 is a cytoskeleton scaffolding protein that coordinates protein assembly, drives axonal branching, influences connectivity in neurons, and is known to play a role in long QT syndrome as a result of abnormal ion channel localization." (PMID 35587487, 2022). "Mutations in ANK2 are responsible for Long QT syndrome but these effects appear to be independent of any association with Nav1.5." (PMID 34281161, 2021).
epilepsy (9 papers, 2017 to 2025). A brain disorder characterized by episodes of abnormally increased neuronal discharge resulting in transient episodes of sensory or motor neurological dysfunction, or psychic dysfunction. "Early detection of ANK2 variants in epilepsy patients is worthwhile considering the potential sudden death risk of this disorder." (PMID 39962910, 2025). "Variants in ANK2 have been anecdotally associated with epilepsy, although the seizure semiology and epilepsy syndromes have not been well characterized." (PMID 39962910, 2025). "Animal models with ANK2 deletion have exhibited seizures and been anecdotally associated with epilepsy in case reports." (PMID 39962910, 2025). "The interactions between OTUD7A and Ankyrin-G (Ank3) and Ankyrin-B (Ank2) were disrupted by an epilepsy-associated OTUD7A L233F variant." (PMID 36604605, 2023). "The OTUD7A protein–protein interaction network included synaptic, axonal, and cytoskeletal proteins and was enriched for ASD and epilepsy risk genes (Ank3, Ank2, SPTAN1, SPTBN1)." (PMID 36604605, 2023). "Another independent group of ANK2 variants are associated with increased risk for distinct neurological phenotypes, including epilepsy and autism spectrum disorders." (PMID 35990955, 2022). "In a study which sequenced cases of epilepsy-related sudden unexpected death for inherited heart disease related genes, one individual was found to carry two variants in ANK2 (p.Ser105Thr, p.Glu1934Val)." (PMID 35990955, 2022). "Furthermore, with the link to epilepsy in neurological-associated ANK2 variants it raises the question of how ANKB dysfunction is impacting neuronal mechanisms." (PMID 35990955, 2022). "Notably, independent of the connection between ANK2 variants and risk for epilepsy, seizures were reported in association with cardiac-phenotype associated ANK2 variants." (PMID 35990955, 2022). "Similarly, in a workflow using the random walk with restart algorithm in addition to permutation and functional association tests ANK2 was also predicted as a novel gene for epilepsy." (PMID 35990955, 2022). "This study reported the first familial ANK2‐related epilepsy, highlighting the role of ANK2 in epileptogenesis." (PMID 39962910, 2025). "In terms of treatment, sodium channel blockers and broad‐spectrum ASM valproate acid, appear to be effective in the treatment of ANK2‐related epilepsy." (PMID 39962910, 2025). "A literature review of ANK2‐related epilepsy demonstrates that the majority of patients (8 out of 10) have young‐onset (<6 years old) self‐limited focal epilepsy or neonatal seizure, which mostly respond well to ASM monotherapy." (PMID 39962910, 2025). "The limitation of this study is the retrospective nature of the literature review and the small number of reported ANK2‐related epilepsy." (PMID 39962910, 2025). "We identified 10 patients (including two reported here) with ANK2‐related epilepsy in the literature." (PMID 39962910, 2025). "Most reported ANK2‐related epilepsies are self‐limited and pharmaco‐responsive, suggesting that they are likely to be underdiagnosed." (PMID 39962910, 2025). "Most (8/10) ANK2‐related epilepsy manifest as young‐onset (aged from 2 months old to 6 years old) self‐limited focal epilepsy." (PMID 39962910, 2025). "Lastly, given that Ank2 has recently been implicated in epilepsy, our results implicate Kv7 pathophysiology in Ank2-related epilepsy." (PMID 37321992, 2023). "ANK2 has been identified as a key risk gene for autism spectrum disorders (ASD) and as a candidate gene for epilepsy." (PMID 35990955, 2022). "Using a multiplex network that characterized modules of epilepsy and ASD genes sharing similar phenotypes and protein-protein interactions, ANK2 has also been identified as a novel candidate gene for epilepsy." (PMID 35990955, 2022). "Most ANK2 related epilepsies are self‐limited and pharmacoresponsive." (PMID 39962910, 2025).